ENSG00000285471 (novel protein)
Gene: Protein-coding gene on chromosome 17 (5,772,926 to 6,080,792, forward strand). Ensembl gene ENSG00000285471.
Genetic constraint (gnomAD): Loss-of-function variants: 5 observed, 4.28 expected, observed/expected ratio (o/e) 1.17, 90% interval 0.59 to 1.88. That is too few expected variants to judge how well the gene tolerates losing a copy. Missense variants: 49 observed, 58.77 expected, observed/expected ratio (o/e) 0.83, 90% interval 0.66 to 1.06. Synonymous variants: 25 observed, 29.01 expected, observed/expected ratio (o/e) 0.86, 90% interval 0.63 to 1.2.